FOXO1 (forkhead box O1)
Diseases named in the same sentence as FOXO1 in open-access papers (continued):
Sharing a sentence is not in itself a finding about the gene and the disease.
iron-overload (3 papers, 2015 to 2019). "CUR, a polyphenol compound, possesses antioxidative and osteogenic activities and was able to attenuate bone loss in iron-overload mice at a relatively lower dose through mediation of the FoxO1 signal pathway." (PMID 31949885, 2019). "Iron-overload increased nuclear and acetylated levels of FOXO1 with corresponding inverse changes in SIRT1 levels in the heart corrected by resveratrol therapy." (PMID 26638758, 2015). "Resveratrol therapy resulted in reduced acetylation of myocardial nuclear FOXO1 in response to iron-overload providing a key molecular basis for RSV therapeutic action." (PMID 26638758, 2015). "We identified the SIRT1/FOXO1 axis as a key pathway involved in iron-overload." (PMID 26638758, 2015).
kidney cancer (3 papers, 2019 to 2025). Primary or metastatic malignant neoplasm involving the kidney. "In the A-498 kidney cancer cell, a positive correlation (p < 0.05) was observed between miR-181a expression and the mRNA expression of FOXO1, FOXO3, PDCD4, AKT3, JNK1 and LAMTOR3." (PMID 41462911, 2025). "Musclin is greatly reduced in skeletal muscle of transgenic mice overexpressing the transcription factor FoxO1, that agrees with its steep downregulation we observed in muscle of C26 mice or more slightly in immunodeficient mice bearing human kidney cancer RXF393." (PMID 31614775, 2019).
leiomyoma (3 papers, 2012 to 2017). A well-circumscribed benign smooth muscle neoplasm characterized by the presence of spindle cells with cigar-shaped nuclei, interlacing fascicles, and a whorled pattern. "In leiomyoma cells, PRs can rapidly activate the PI3K/AKT pathway and its effectors, such as p-GSK3β and p-FOXO1." (PMID 28930160, 2017). "In line, R5020, a synthetic progestin acting as a PR agonist, was shown to induce proliferation of leiomyoma cells in vitro, through the phosphorylation of the downstream targets of AKT (FOXO1 and GSK3β)." (PMID 28930160, 2017).
lentivirus infection (3 papers, 2017 to 2023). Virus diseases caused by the Lentivirus genus. "A mTORC2 inhibitor, JR-AB2-011, reversed the effects of anti-miR-582 on AKT and FoxO1 phosphorylation, and abrogated increased pre-B cell proliferation and survival upon anti-miR-582 lentivirus infection." (PMID 35115499, 2022). "Foxo1 knocked down but not control lentivirus infection induced CD19‐deficient MZP cells (CD21hiIgMhiCD1dhiCD23+IgDhi) to produce MZ B cells (CD21hiIgMhiCD1dhiCD23−IgDlo)." (PMID 28707394, 2017).
liver cirrhosis (3 papers, 2018 to 2025). "However, in the present study carried out in cirrhotic patients after partial hepatectomy, we showed that Akt and its target FoxO1 are overexpressed in liver cirrhosis." (PMID 38075169, 2023).
lymphopenia (3 papers, 2016 to 2024). Reduction in the number of lymphocytes. "In vivo transferred T-cells up-regulate expression of Bcl-2, FoxO1, Eomes and Atg7, enhance the phosphorylation of pSTAT5 and ULK1 and activate the mitochondrial biogenesis via IL-15 signaling in lymphopenia." (PMID 27158441, 2016).
mesothelioma (3 papers, 2015 to 2025). A usually malignant and aggressive neoplasm of the mesothelium which is often associated with exposure to asbestos. "In the present study, we analyzed the role of FOXO1 by conducting cell proliferation and invasion assays using FOXO1-siRNA in mesothelioma cells treated with miR-182 and miR-183 inhibitors and demonstrated the association between FOXO1 and mesothelioma cell proliferation and invasion." (PMID 30406026, 2018). "For example, miR‐182 and miR‐183 promote mesothelioma cell proliferation, invasion, and adhesion via the FOXO1 signaling pathway, and their inhibition significantly impairs these malignant properties." (PMID 40904706, 2025). "In conclusion, we demonstrated that miR-182 and miR-183 promote cell proliferation and invasion by targeting FOXO1 in mesothelioma cells." (PMID 30406026, 2018). "Mesothelioma cells treated with miR-182 and miR-183 inhibitors showed upregulated mRNA and protein expression of FOXO1." (PMID 30406026, 2018). "Our current findings identified FOXO1 as a target of both miR-182 and miR-183 in mesothelioma cells." (PMID 30406026, 2018). "Mesothelioma cells treated with FOXO1 siRNA and miR-182/183 inhibitors were also analyzed by evaluating cell proliferation and invasion, as well as expression of FOXO1 and its downstream targets." (PMID 30406026, 2018). "Our findings indicated that miR-182 and miR-183 promote mesothelioma cell progression via downregulation of FOXO1 and p27." (PMID 30406026, 2018). "In the present study, we investigated the biological roles of miR-182 and miR-183 and their target, FOXO1, in mesothelioma cells." (PMID 30406026, 2018). "To verify whether FOXO1 is a target of miR-182 and miR-183 in mesothelioma cells, we conducted RT-PCR and western blot analysis of cells treated with miRNA inhibitors." (PMID 30406026, 2018). "Therefore, our findings indicated that miR-182/183 acts through the FOXO1-p27 axis in proliferation of mesothelioma cells." (PMID 30406026, 2018). "To determine whether miR-182 and miR-183 inhibit mesothelioma cell proliferation and invasion by suppressing FOXO1 expression, we conducted cell proliferation and invasion assays by co-transfecting ACC-MESO1 and CRL-5915 cells with microRNA inhibitors and siRNAs." (PMID 30406026, 2018). "Furthermore, FOXO1 was identified as a target of miR-182 and miR-183 in mesothelioma cells." (PMID 30406026, 2018). "Results showed that p21 and p27 expression levels were upregulated in mesothelioma cells treated with miR-182 and miR-183 inhibitors, and the observed upregulation of p27 was reversed by FOXO1 knockdown but not p21." (PMID 30406026, 2018). "Cell proliferation and invasion were not significantly reduced in cells transfected with FOXO1 siRNA despite the observed miRNA inhibition upon treatment with miR-182 and miR-183 inhibitors when compared to mesothelioma cells transfected with negative control siRNA." (PMID 30406026, 2018).
Myocardial fibrosis (3 papers, 2021 to 2024). "Besides, the protein expressions of LC3-II and Beclin1 were lower while that of p62 was higher in the AS group than the DM group, indicating that FoxO1 is one key factor in regulating myocardial fibrosis, apoptosis and autophagy in diabetic mice." (PMID 34522203, 2021).
pulmonary fibrosis (3 papers, 2018 to 2024). Chronic progressive interstitial lung disorder characterized by the replacement of the lung tissue by connective tissue, leading to progressive dyspnea, respiratory failure, or right heart failure. "The deactivation of FoxO1 was linked to bleomycin-induced pulmonary fibrosis." (PMID 37367427, 2023). "Induction of FoxO1 attenuated airway remodeling by reducing M1 macrophage activation-induced inflammatory cytokine expression and the progression of pulmonary fibrosis." (PMID 39451243, 2024).
rectal cancer (3 papers, 2014 to 2024). A primary or metastatic malignant neoplasm that affects the rectum. "miR-223 has an anti-proliferative function in cervical and colon-rectal cancer through the targeting of IGFR and FOXO1 and it exerts an anti-metastatic role in oesophageal carcinoma." (PMID 24400121, 2014).
retinoblastoma (3 papers, 2015 to 2018). A malignant tumor that originates in the nuclear layer of the retina. "Deleting PTEN activates p-AKT and enforces FOXO1 inactivation, thereby allowing E2Fs to continue their proliferative, but not apoptotic, target gene induction, which causes rapid bilateral retinoblastoma emergence." (PMID 25907958, 2015). "We conclude that the AKT signaling pathway is activated in human retinoblastomas and significantly correlates with p-FOXO1 and Ki-67 staining in these tumors." (PMID 28445155, 2017). "Co-activation of Akt and FOXO1 phosphorylation is also a common feature in proliferating human retinoblastoma tumor cells." (PMID 28445155, 2017). "Fisher's exact test computed a two-tailed P-value of 0.002 for this contingency table, indicating that human retinoblastomas with high levels of p-Akt are also highly positive for p-FOXO1." (PMID 28445155, 2017). "Human retinoblastoma tumors displayed significant correlation between p-AKT intensity with highly proliferative tumors (p = 0.008) that were also highly positive for p-FOXO1 (p = 0.002)." (PMID 28445155, 2017). "In vivo electroporation of constitutively active (ca)-Pik3ca, ca-Akt, or dominant-negative (dn)-Foxo1 into apoptosis prone newborn murine retina with deleted Rb/p107 eliminate Rb/E2F induced apoptosis and induce retinoblastoma emergence." (PMID 25907958, 2015). "We used IHC staining for Ki-67, Caspase-3, terminal dUTP nick end labeling (TUNEL), p-AKT and p-FOXO1 to clarify how loss of PTEN and RB/p107 in the retina controls apoptosis and induces retinoblastoma." (PMID 25907958, 2015). "Targeted studies on retinoblastoma mouse models showed that Rb1 loss and additional oncogenic stress including PTEN loss led to the activation of Akt and the subsequent inactivation of FOXO1, leading to tumour proliferation." (PMID 29914080, 2018). "It is unclear why AKT targets p-FOXO1 more strongly than p-S6 in human retinoblastoma." (PMID 28445155, 2017). "We further analyzed the correlation between p-AKT and p-FOXO1 activation in human retinoblastoma." (PMID 28445155, 2017). "We evaluated whether E2F1 requires FOXO1 to induce pro-apoptotic target gene expression in Y79 human retinoblastoma cells transfected separately with control or two FoxO1 siRNAs." (PMID 25907958, 2015). "Retinal deletion of Pten activates p-AKT and p-FOXO1 signaling in incipient retinoblastoma." (PMID 25907958, 2015). "Important mediators of the insulin pathway such as Akt, BCL-2 antagonist of cell death (BAD), FOXO1, and FASN were found to be phosphorylated in both retina and retinoblastoma tissues." (PMID 29914080, 2018). "Particularly, we identified Akt, FOXO1, and BAD to be phosphorylated in retina and retinoblastoma tissues." (PMID 29914080, 2018). "FOXO1, a direct target of AKT, is highly phosphorylated and thus inactivated in human retinoblastoma tumors that also had high p-AKT levels." (PMID 28445155, 2017). "The relative staining intensity of p-Akt, Ki-67, p-FoxO1, and p-S6 was scored for each individual retinoblastoma ranging from 0 (no staining) to 4 (most intense staining)." (PMID 28445155, 2017). "Serial sections from human retinoblastoma tissue microarrays containing 27 tumors were stained with antibodies specific to p-AKT, Ki-67, forkhead box O1 (p-FOXO1), and ribosomal protein S6 (p-S6) using immunohistochemistry and each tumor sample scored for intensity." (PMID 28445155, 2017).
tendinopathy (3 papers, 2020 to 2024). "Our study suggested that FOXO1 affected tendinopathy progression by regulating PRDX2 transcriptional activity." (PMID 37223090, 2023).
thrombosis (3 papers, 2020 to 2023). "Moreover, SIRT1/FOXO1 signaling pathway has been identified as a promising target to prevent VWF-mediated arterial thrombosis." (PMID 37415610, 2023). "SIRT1/FoxO1 could be a promising target for preventing AS and arterial thrombosis." (PMID 35607519, 2022).
uveitis (3 papers, 2020 to 2025). An inflammatory process affecting a part of or the entire uvea. "However, few studies have determined the function of the PI3K/AKT/FoxO1 pathway in the pathogenesis of uveitis." (PMID 33281814, 2020).
acute respiratory distress syndrome (2 papers, 2022 to 2025). Progressive and life-threatening pulmonary distress in the absence of an underlying pulmonary condition, usually following major trauma or surgery. "Pomiferin, a compound belonging to the isoflavonoid class, could block the Akt/forkhead box protein O1 (FOXO1) signaling pathway, and suppress inflammation and oxidative harm, showing potential benefits for acute respiratory distress syndrome." (PMID 41333774, 2025).
B-acute lymphoblastic leukemia (2 papers, 2022 to 2024). "Taking hematological tumors as an example, Köhrer found that in B-acute lymphoblastic leukemia, cell signaling activates the FOXO1 pathway and inhibits the occurrence and development of B-cell tumors, indicating that FOXO1 plays an anti-tumor role in B-ALL." (PMID 36290822, 2022).
brain injury (2 papers, 2021 to 2024). Acute and chronic (see also brain INJURIES, CHRONIC) injuries to the brain, including the cerebral hemispheres, CEREBELLUM, and brain STEM. "For example, further investigation showed that the increase of FoxO1 is closely related with the inhibition of necroptosis in microglia cells after traumatic brain injury." (PMID 34661985, 2021).
brain tumor (2 papers, 2007 to 2018). "Interestingly, in contrast with the other tumors, slight significant overexpression of FOXO1 was observed in brain tumours, and the expression of FOXO3 was found to be overexpressed in some of these tumors." (PMID 29484124, 2018).
cholangiocarcinoma (2 papers, 2020 to 2022). A carcinoma that arises from the intrahepatic biliary tree (intrahepatic cholangiocarcinoma) or from the junction, or adjacent to the junction, of the right and left hepatic ducts (hilar cholangiocarcinoma). "FOXO1 silencing or Sirt1 inhibition, affected autophagic flux, impaired mitochondrial function and induced apoptosis in a cholangiocarcinoma cell line, suggesting a role of Sirt1/FOXO1 pathway in the interplay between autophagy and mitochondrial dysfunction in CCA." (PMID 32138158, 2020).
cholestasis (2 papers, 2020 to 2025). Impairment of the bile flow caused by obstruction within the liver, or outside the liver in the bile duct system. "Moreover, Schisandrol B reduces atypical cell death induced by Apoptotic protease-activating factor 1 (Apaf-1) inflammasomes through the PXR/Forkhead box protein O1 (FoxO1)/Apaf-1 axis, thereby mitigating cholestasis-induced liver damage." (PMID 40832608, 2025). "In cholestasis, cholangiocytes undergo a process of activation also known as ductular reaction, in which the cell proliferation rate is abnormally increased, and FOXO1, a member of FOXO family of transcription factors with roles in cell fate regulation, is expressed in cholangiocytes." (PMID 32994489, 2020).
cognitive decline (2 papers, 2020 to 2021). "Its overexpression alleviated cognitive decline, reduced accumulation of Aβ, and slowed pericyte loss by targeting FOXO1." (PMID 33790780, 2021). "In our study, the histamine 2/3 receptor agonists inhibited exploratory laparotomy- or LPS-induced cognitive decline, microglia activation, proinflammatory cytokine production, NF-κb expression, M1/M2 phenotype transformation, cell migration, and TLR4 expression through the PI3K/AKT/FoxO1 pathway." (PMID 32698899, 2020).
emphysema (2 papers, 2023 to 2024). "The results of RT-qPCR indicated that the mRNA expression level of FOXO1 in the lung tissue of emphysema mice was elevated compared with AIR group mice, and the mRNA expression level of DDX17 was also increased." (PMID 38802460, 2024). "In addition, PCA administration ameliorated FoxO-1 elevation, increased Nrf2 gene expression, and reduced air alveoli emphysema, bronchiolar epithelium hyperplasia and inflammatory cell infiltration induced by CP." (PMID 36877411, 2023). "The results of RT-qPCR and Western Blot indicate that the mRNA and protein expression levels of FOXO1 and DDX17 in lung tissue of emphysema mice were significantly higher compared with those in air-exposed mice." (PMID 38802460, 2024). "Lastly, the verification of mRNA and protein expression levels in the lung tissue ofmouse emphysema model may only indicate that FOXO1 and DDX17 are related to regulatory genes of T-cell immune responses, but it does not mean that FOXO1 and DDX17 are direct regulatory genes of T-cell function." (PMID 38802460, 2024).
esophageal adenocarcinoma (2 papers, 2018 to 2025). A malignant tumor with glandular differentiation arising predominantly from Barrett mucosa in the lower third of the esophagus. "Our study shows that FOXO1 overexpression and loss of pSerine256-FOXO1 expression are associated with poor prognosis in esophageal adenocarcinomas." (PMID 30478420, 2018).
female infertility (2 papers, 2022 to 2023). Diminished or absent ability of a female to achieve conception. "Our results suggest that aberrant KRAS/FOXO1/BMP7 signaling in theca cells is likely an important cause of anovulation and female infertility." (PMID 36060690, 2022). "Mice lacking FOXO3 manifest age-related female infertility, whereas targeted disruption of FOXO1 leads to midgestational death, attributed to abnormal vascular/cardiovascular morphogenesis." (PMID 37835658, 2023).
fertility disorders (2 papers, 2020 to 2025). "The reduction in SIRT1/FOXO1 testicular expression levels in the varicocele group suggests a correlation between varicocele-related fertility disorders and the SIRT1/FOXO1/OS axis." (PMID 40524181, 2025). "We have previously reported a Cep55-overexpression mouse model that exhibits male-specific sterility by suppressing Foxo1 nuclear retention through hyperactivation of Pi3k/Akt signaling." (PMID 33087841, 2020).
Hearing impairment (2 papers, 2020 to 2024). A decreased magnitude of the sensory perception of sound. "FOXO1 acts as a direct upstream regulator of NCOA4, inhibiting NCOA4‐mediated ferritinophagy and alleviating cisplatin‐induced SGN ferroptosis and hearing loss." (PMID 39206719, 2024).
hematoma (2 papers, 2025). A hematoma is a collection of blood from a vascular structure into an extravascular space. "The identification of FOXO1-driven CD8+ T cells that undergo metabolic reprogramming within the hematoma has not only revealed the impact of the hematoma microenvironment on T cells but also revealed a novel functional state of these cells in acute ICH." (PMID 41238793, 2025).
high-grade glioma (2 papers, 2013 to 2024). "Since high-grade glioma (HGG) patients had much lower survival expectancy after surgery than low-grade glioma (LGG), we performed sub-group analysis to investigate FOXO1 and pFOXO1 expression on prognosis of the group of patients with dismal prognosis." (PMID 23874926, 2013).
keloid (2 papers, 2021 to 2023). An irregularly shaped, elevated mark on the skin caused by deposits of excessive amounts of collagen during wound healing. "The expression of FoxO1 is highly increased in fibroblasts and inflammatory cells in keloid scars and the gene expression levels of several wound growth factors, including FGF2, Notch1, and ADIPOQ, are also decreased in keloid scars." (PMID 34418600, 2021).
laryngeal carcinoma (2 papers, 2022 to 2025). Carcinoma that arises from the laryngeal epithelium. "Noncoding RNAs such as miR-132 can promote laryngeal cancer proliferation and growth via targeting FOXO1, resulting in the activation of PI3K/AKT pathway." (PMID 40231252, 2025). "FoxO1 serves a necessary function in HDAC inhibitor‐based suppression of larynx carcinoma invasion and metastasis by blocking MMP7 or by binding the ZEB2 promoter and reversing ZEB2‐induced EMT." (PMID 33772986, 2022).